LMO1 (LIM domain only 1)
Diseases named in the same sentence as LMO1 in open-access papers (continued):
Sharing a sentence is not in itself a finding about the gene and the disease.
cancer (20 papers, 2013 to 2025). A tumor composed of atypical neoplastic, often pleomorphic cells that invade other tissues. "An increasing number of publications have identified that LMO1 plays a determinant role in cancer susceptibility." (PMID 38937681, 2024). "Four polymorphisms in LMO1 (rs110419 A>G, rs4758051 G>A, rs10840002 A>G and rs204938 A>G) were found to be associated with the risk of several cancers in a genome-wide association study (GWAS)." (PMID 28881592, 2017). "There is overwhelming evidence that LMO1 is a critical determinant of cancer susceptibility." (PMID 28881592, 2017). "Through these activities, LMO1 has important cellular roles in processes that are relevant to cancer such as self-renewal, cell cycle regulation and metastasis." (PMID 35563322, 2022). "Recent studies have shown that LMO1 functions as an oncogene in several cancer types, including non-small cell lung cancer (NSCLC)." (PMID 30038707, 2018). "After validating μ-cisTarget on the TAL1, LMO1, and TERT mutations, we analyzed ten widely used cancer cell lines as a discovery set." (PMID 28854983, 2017). "This suggests that dysregulation of LMO1 may be important to the development of cancers of neural origin." (PMID 30038707, 2018). "More recently, LMO1 has been reported to have an oncogenic role in other types of cancer." (PMID 30038707, 2018). "It was reported that TGF-β induced LMO1 via the Smad-dependent signaling pathway, which in turn mediates TGF-β-induced EMT and plays a central part in controlling the metastasis of cancer." (PMID 35342421, 2022). "Our analysis identified LMO1 and PRAME as promising prognostic biomarkers in BC patients, thereby validating our framework as a robust, generalizable approach for discovering prognostic biomarkers in cancer." (PMID 40076569, 2025). "The genes—including BEST4, LMO1, ARID3C, TMEM44, FKBP10, and TRIB3—were correlated with VSX1 and might play a primary role in the transcriptional misregulation of cancer from the TCGA database." (PMID 36463181, 2022). "We identified non-coding hotspots upstream of three known T-ALL oncogenes (LMO1, LMO2, and TAL1), demonstrating that hotspot detection could be useful even in small cancer cohorts." (PMID 32550006, 2020). "Moreover, TGFβ up-regulates GSDMA expression through lmo1, and the resultant GSDMA overexpression induces apoptosis in human cancer cell lines." (PMID 23979942, 2013).
adenocarcinoma (1 paper, 2018). A common cancer characterized by the presence of malignant glandular cells. "In multivariate analysis of the determinants of patient survival, we identified LMO1 as an independent predictor in Caucasian patients with stage I or stage II adenocarcinoma without adjuvant or neoadjuvant chemotherapy." (PMID 30038707, 2018).
infection (1 paper, 2023). The state of being infected such as from the introduction of a foreign agent such as serum, vaccine, antigenic substance or organism. "We used qPCR to analyze 12 host-related genes, including those with no significant fold change (IL12A), modest (e.g. TNF, LMO1, IL10, CCL2, IL1B) or high fold change, including CXCL8 which was among the 50 identified to be most significantly dysregulated in monocytes as a result of infection." (PMID 36747074, 2023).
LMO1 also shares sentences with these, for which no sentence is quoted: colorectal cancer (3 papers); chronic lymphocytic leukaemia (2); Obesity (2); acute leukemia (1); alopecia areata (1); B-cell lymphoma (1); Crohn disease (1); esophageal cancer (1); large cell neuroendocrine lung carcinoma (1); myeloid leukemia (1); neuroendocrine carcinoma (1); non-small cell lung carcinoma (1); prostate carcinoma (1); sickle cell anaemia (1); small cell lung carcinoma (1); squamous cell carcinoma (1); systemic lupus erythematosus (1); thymic lymphomas (1).